ACE (angiotensin I converting enzyme)
Diseases named in the same sentence as ACE in open-access papers (continued):
Sharing a sentence is not in itself a finding about the gene and the disease.
angioedema (continued). "ACEi-AE is a rare adverse effect associated with the use of ACE inhibitors affecting 0.1% to 0.7% of treated patients, which accounts for 30% of all angioedema cases." (PMID 34692327, 2021). "Acquired forms of BK-mediated angioedema, such as that associated with angiotensin-I converting enzyme (ACE) inhibition, are also known." (PMID 32824891, 2020). "For example, ACE inhibitors cause cough and angioedema, ARBs also cause slight cough and angioedema sometimes, β-blockers usually cause insomnia, hallucinations, and depression, and CCBs usually cause ankle edema, headache, flushing, and tachycardia." (PMID 31894475, 2020). "The assumed underlying pathomechanism of ACEi-associated angioedema is the accumulation of bradykinin through inhibition of ACE (angiotensin converting enzyme)." (PMID 32214375, 2020). "While known serious side effects of all ACE inhibitors include angioedema and hyperkalemia, ACE inhibitor-associated hyponatremia has been rarely reported." (PMID 32782860, 2020). "The most severe symptom associated with ACE inhibitors angioedema occurs in 0.55–1.62% of patients according to the Octave study." (PMID 31655853, 2020). "Until now, the exact mechanism of ACE inhibitors in angioedema is yet to be fully explained; but the structural relationship between ACE and inhibitors is clearly implicated." (PMID 30998765, 2019). "Bradykinin induced angioedema includes all types of hereditary angioedema, acquired C1-esterase inhibitor deficiency and angiotensin converting enzyme (ACE) inhibitor induced angioedema." (PMID 31338156, 2019). "ACE inhibitors together with sacubitril increase the risk for angioedema which is a serious but rare adverse event." (PMID 31772613, 2019). "The diagnostic workup of angioedema should exclude the possibility of acquired angioedema, i.e. ACE-inhibitor associated angioedema (ACEI-AAE), acquired C1-deficiency angioedema (C1-INH-AAE) and acquired non-histaminergic angioedema (InH-AAE)." (PMID 30809376, 2019). "It should be noted that we included a limited number of mainly white patients who tolerated target doses of ACE inhibitors/ARBs and this patient group has a low absolute risk to develop angioedema." (PMID 31772613, 2019). "Angiotensin-converting enzyme (ACE) inhibitors are considered one of the most frequent causes of acquired angioedema, accounting for 25–40% of all cases of angioedema." (PMID 30514395, 2018). "These are angioedemas caused by ACE inhibitors, some idiopathic angioedemas, and hereditary angioedema with normal C1-INH (HAE type III)." (PMID 31826031, 2018). "In most cases, ACE inhibitors caused side effects are mild; however, from 0.1% to 0.7% of patients can develop life threatening adverse effect, angioedema." (PMID 30075570, 2018). "Consistent with previous studies, ACE inhibitor use was associated with a higher risk of developing angioedema." (PMID 30363665, 2018). "This case is unusual because angioedema caused by perindopril, a known ACE inhibitor, is an unusual occurrence in Saudi Arabia." (PMID 30514395, 2018). "The period of time between start of medication and onset of the first angioedema can vary from months and several years so that the association between angioedema and ACE inhibitors is sometimes only recognized quite late." (PMID 31826031, 2018). "So far, only four cases of angioedema caused by ACE inhibitors have been reported to the National Pharmacovigilance and Drug Safety Center at the Saudi Food and Drug Authority by different hospitals in Saudi Arabia." (PMID 30514395, 2018). "Numerous study results suggest that bradykinin is responsible for the development of angioedemas caused by ACE inhibitors." (PMID 31826031, 2018). "Treatment of TF patients with a combination of ACE inhibitor and angiotensin II receptor blockers shows limited efficacy and can be associated with persistent cough, angioedema, stenosis, birth defects, and renal failure." (PMID 30405320, 2018).
angioedema (continued). "Angioedema is associated with the use of angiotensin-converting enzyme (ACE) inhibitors, which is found in 45% of patients with angioedema." (PMID 30018956, 2018). "During ACE inhibition, accumulation of Substance P doesn’t cause angioedema because it is inactivated by DPP-IV." (PMID 29067222, 2017). "The current meta-analysis of the side effects of pharmaceutics for treatment of cardiovascular diseases in those patients revealed a relative risk for the manifestation of ACE inhibitor-induced angioedema that was three times higher than in white Americans." (PMID 28025602, 2016). "Having been on an ACE inhibitor increases his chances of having angioedema; however, it is likely that repeated exposure to tPA increases the likelihood of angioedema and emergency physicians should be aware of this risk." (PMID 25671036, 2015). "There are risk factors for oral angioedema that should be evaluated in patients taking ACE inhibitors: older age, femal sex, Hispanic race, or African-American ancestry." (PMID 25431681, 2014). "Cough and angioedema, two adverse drug reactions typically associated with ACE-inhibition and two of the major causes of withdrawal from ACE-inhibitor trials, are usually more frequently observed in women than in men." (PMID 25364906, 2014). "Before the surgery, patients with increased risk factors for severe cases of angioedema should withdraw ACE inhibitor as early as possible." (PMID 25431681, 2014). "Several studies have shown that treatment with ARBs is associated with significantly lower rates of cough and angioedema versus ACE inhibitors." (PMID 22490507, 2012). "• ACE inhibitors should be discontinued in any individual who presents with angioedema as this condition is associated with life-threatening upper airway angioedema." (PMID 22165855, 2011). "Another example of a well-known rare and serious adverse event associated with an effective medication is ACE-inhibitor-associated angioedema." (PMID 21129189, 2010). "In a New Zealand study, the authors reviewed reports of angioedema and urticaria associated with ACE inhibitors." (PMID 20180980, 2010). "Genetic variants in the gene encoding APP (XPNPEP2), resulting in reduced enzyme activity, higher bradykinin and des-Arg9-BK have been associated with angioedema induced by ACE inhibitors." (PMID 20667119, 2010). "In contrast to C1 INH deficiency or ACE-induced angioedema, angioedema can be prevented with corticosteroid when other approaches have failed." (PMID 23282406, 2008). "It is also advisable to check the complement C4 level because patients with preexisting angioedema, including HAE caused by C1 esterase inhibitor deficiency, are predisposed to develop angioedema in response to ACE inhibitors." (PMID 23282406, 2008). "Bradykinin is the mediator of angioedema associated with angiotensin-converting enzyme (ACE) inhibitors that prevent bradykinin destruction so that levels rise." (PMID 23282406, 2008). "Anaphylaxis, angioedema due to an ACE inhibitor, or C1 INH deficiency are the circumstances where true stridor and respiratory embarrassment can occur, and intubation or tracheostomy becomes necessary." (PMID 23282406, 2008). "Researchers have suggested that reduced DPP-4 enzyme activity and DPP-4 enzyme deficiency increase ACE inhibitor-induced angioedema in rats and potentially humans." (PMID 18954434, 2008). "A dual ACE and neutral peptidase inhibitor, omapatrilat, carries an even higher risk of angioedema than pure ACE inhibitors alone." (PMID 23282406, 2008). "The drugs most commonly associated with angioedema include angiotensin converting enzyme (ACE) inhibitors, other kininase (such as neprilysin or dipeptidyl peptidase IV [DPPIV]) inhibitors, tissue plasminogen activators, and non-steroidal anti-inflammatory drugs (NSAIDs)." (PMID 40053270, 2025). "It appears to cause recurrent angioedema in patients who are also heterozygous for ACE c.1459C > T." (PMID 40053270, 2025).
angioedema (continued). "While ACE inhibitors are commonly implicated, recent reports suggest angiotensin II receptor blockers (ARBs) may also trigger angioedema." (PMID 40636633, 2025). "However, the increased levels of bradykinin are also associated with side effects, such as dry cough and angioedema, which are common in patients using ACE inhibitors." (PMID 39452857, 2024). "The exploration of alternative drug options such as angiotensin II receptor blockers, the potential association of coadministration of DPP-4 inhibitors with ACE inhibitors, the presentation of angioedema and the significant clinical importance of this condition are also discussed." (PMID 38543146, 2024). "Furthermore, inhibition of either DDP-IV or NEP in conjunction with ACE inhibition increases the risk of angioedema even further." (PMID 38332896, 2024). "Notably, people of African descent explore an increased susceptibility to ACE inhibitor-induced angioedema, experiencing up to five times more frequent episodes." (PMID 38543146, 2024). "ACE inhibitor-induced angioedema is one of the most common causes for emergency treatment of angioedema; it occurs in approximately 0.1–6% of individuals using ACE inhibitors and tends to occur more commonly in ACE inhibitor users who are female, smokers, or of African-American descent." (PMID 39654054, 2024). "Similarly, co-administration of DDP4 inhibitors (gliptins) with ACE inhibitors has been linked to a ninefold higher risk of angioedema." (PMID 38543146, 2024). "The more common causes are ACE inhibitor-induced angioedema and idiopathic/spontaneous angioedema." (PMID 39654054, 2024). "This review explores management strategies such as fresh frozen plasma, icatibant, ecallantide, and C1 inhibitor concentrate, and considers alternative drug options like angiotensin II receptor blockers and potential associations of DPP-4 inhibitors with ACE inhibitor-induced angioedema." (PMID 38543146, 2024). "Additionally, Tie-2, FAP-α, tPA, sE-selectin, and Ang-2 have been identified as promising biomarkers for differentiating between hereditary angioedema, ACE inhibitor-induced angioedema, and angioedema associated with chronic spontaneous urticaria." (PMID 38543146, 2024). "Additionally, ACE inhibitor-induced cough, a well-recognized side effect of ACE inhibitors, has been suggested as a risk factor for ACE inhibitor-induced angioedema." (PMID 38543146, 2024). "Furthermore, the use of mTOR inhibitors such as sirolimus and everolimus in patients receiving ACE inhibitors has been linked to an increased incidence of angioedema." (PMID 38543146, 2024). "Furthermore, the use of the pharmacological DPP-IV inhibitor vildagliptin has been associated with an increased risk of angioedema in patients treated with ACE inhibitors." (PMID 38205154, 2024). "Additionally, a meta-analysis of genome-wide association studies assessing genetic risk factors for ACE inhibitor-induced angioedema proposed, for the first time, the involvement of fibrinolysis in the development of angioedema." (PMID 38543146, 2024). "In addition to HAE, bradykinin-mediated angioedema can be caused by certain medications, such as angiotensin-converting enzyme inhibitors (ACE inhibitors) and dipeptidyl peptidase-4 inhibitors (gliptins)." (PMID 37920409, 2023). "Other risk factors associated with ACE inhibitor-associated angioedema include smoking history, seasonal allergies, antihistamine use, and corticosteroid use, with studies showing an increased number of presentations during the months with higher pollen counts." (PMID 38957198, 2023). "The commercially available synthetic ACE inhibitors (enalapril, lisinopril, etc.)cause side effects like nausea, hyperkalemia, headache, swelling of the lower portion of the skin, cough, disturbances in taste, and angioneurotic edema." (PMID 37324400, 2023).
angioedema (continued). "Briefly, Black African and Mixed Ancestry participants in the study who were carriers of the −9/+9 genotype had ACE-induced angioedema or cough and this association remained true upon further analysis in the dominant model, which implicated the B2 −9 allele to the observed associations." (PMID 38633331, 2023). "ACE inhibitor-associated angioedema has a predilection for the lips, tongue, face, and upper airway, which may progress to airway obstruction." (PMID 38957198, 2023). "Similarly, another treatment option for HAE that has proven ineffective in ACE inhibitor-associated angioedema is ecallantide, a kallikrein inhibitor." (PMID 38957198, 2023). "Notably, ARBs have a lower risk of angioedema and cough and are a good option for patients who have demonstrated intolerance to ACE inhibitors." (PMID 38161537, 2023). "Moreover, in patients who regularly use NSAIDS, ACE inhibitors, or angiotensin receptor blockers, oral grafts are relatively contraindicated, as they have been associated with angioedema of oral mucosa." (PMID 35407672, 2022). "ACE inhibitors are closely associated with bradykinin-related angioedema." (PMID 33398469, 2021). "There are several causes of drug-induced angioedema, one being ACE inhibitor-induced angioedema." (PMID 34884209, 2021). "Importantly, this is the main reason that development of a dual ACE/neprilysin inhibitor omapatrilat was halted, because the use of this drug was associated with considerably higher incidence of angioedema in patients with cardiovascular disorders." (PMID 33687143, 2021). "It has been supposed that genetic or environmental factors that reduce the activity of DPP-IV or other non-ACE enzyme pathways responsible for the inactivation of such vasoactive peptides are likely to augment the susceptibility to angioedema during exposure to ACEIs." (PMID 34872575, 2021). "Again the NEPi and ACE inhibitor combination predisposes a high risk of angioedema." (PMID 31336656, 2019). "Furthermore, caution must be applied when using ACE inhibitors in the setting of tPA administration as there is an increased risk of orolingual angioedema which is uncommon though can be life-threatening." (PMID 30846967, 2019). "The incidence of angioedema caused by the use of ACE inhibitors has been increasing over the last two decades; this is because these drugs are consumed by individuals worldwide for the management of heart failure, renal failure, myocardial infarction, and nephropathy due to diabetes mellitus." (PMID 30514395, 2018). "For this reason, ACE inhibitors should be stopped, if possible, before administration of tPA, and ACE inhibitors in themselves should be considered as a main risk factor for the development of tPA-induced angioedema." (PMID 30363665, 2018). "However, the association of the rs989692 variant of the neprilysin gene with ACE inhibitor-associated angioedema is evidence for a role for neprilysin in the regulation of bradykinin levels in humans." (PMID 30283782, 2018). "Further, drug-induced angioedema/anaphylactoid states, including those associated with ACE inhibitor or recombinant tissue plasminogen activator (tPA) administration, may involve kinin generation and kinin receptor stimulation." (PMID 30333824, 2018). "In proven C1-INH-HAE, genetic testing of APP and ACE deficiencies could potentially help in identifying patients with more frequent or more severe angioedema attacks." (PMID 30479631, 2018). "Its presence should alert the physician to alternative diagnoses, which could comprise life-threatening conditions including hereditary angioedema (HAE), acquired angioedema (AAE), or angioedema associated with angiotensin-converting enzyme (ACE) inhibitors." (PMID 30263036, 2018). "Substance P is involved in ACE inhibitor (ACEI) associated angioedema." (PMID 29067222, 2017).
angioedema (continued). "The present study illustrates that clinical awareness for this condition and adequate use of radiologic investigations can help make the correct diagnosis of ACE inhibitor-associated angioedema, thus avoiding the cost and morbidity associated with unnecessary interventions." (PMID 28133581, 2016). "XPNPEP2 (OMIM: 300145) has been implicated in ACE inhibitor-induced angioedema." (PMID 24784881, 2014). "Angiotensin-converting enzyme (ACE) inhibitors are the leading cause of a drug-induced angioedema." (PMID 25431681, 2014). "The more common causes are ACE inhibitor-induced angioedema and idiopathic angioedema." (PMID 22165855, 2011). "ACE DD genotype had been associated with angioedema-ACE inhibitors induced." (PMID 20180980, 2010). "But, the combined ACE/NEP inhibition increases the risk of angioedema and may counteract any benefit of ACE inhibition." (PMID 21042458, 2010). "A study group proposed that ACE gene polymorphism and some enzyme deficiencies could be involved in ACE inhibitor-induced angioedema." (PMID 20180980, 2010). "These authors hypothesized that the concomitant use of DPP-4 inhibitors and ACE inhibitors could increase the risk of angioedema-related adverse experiences." (PMID 18954434, 2008). "The ACE inhibitors are often overlooked as a cause of angioedema, and this may lead to unfortunate consequences because continuing administration tends to lead to more severe attacks." (PMID 23282406, 2008). "The ACE inhibitor angioedema is the most common cause of acute angioedema in accident and emergency hospital departments (17%-38%), and up to 20% may be life threatening." (PMID 23282406, 2008). "ACE inhibitors induce angioedema in 0.1–0.7% of recipients, and although the rate is relatively low, the wide use of these drugs, with more than 40 million patients receiving them on a daily basis worldwide, makes them the most common cause of drug-induced angioedema." (PMID 38543146, 2024). "In addition to haemorrhage, other adverse effects include allergy and angioedema, in which angioedema may be caused by using ACE inhibitors." (PMID 38286483, 2024). "Developing a clinical tool to assess the risk of ACE inhibitor-induced angioedema could revolutionize clinical decision making, potentially saving lives by guiding clinicians to select alternative antihypertensive drugs that pose lower risks for susceptible patients." (PMID 38543146, 2024). "Thus, genetic variation in genes encoding these proteins has been the subject of a number of pharmacogenetic studies which have reported associations of genetic variants with ACE inhibitor-induced adverse events such as angioedema or cough and also BP response." (PMID 38633331, 2023). "Hence, the concomitant selective blockade of Ang II receptors with an ARB prevents the potential effect of excess Ang II, whereas combining an NEP inhibitor with an ACE-i has been shown to cause unacceptably high rates of angioedema since both NEP and ACE contribute to breakdown of bradykinin." (PMID 34497530, 2021). "Although they have a tight binding pattern with the generic ACE active sites (Zn2+, S1, S1’, and S2’ pockets) and exhibit excellent cardiovascular therapeutic capabilities, ACE inhibitors have numerous side effects that can impair renal function, cause hyperkalemia, and develop angioedema." (PMID 31454889, 2019). "Reduced DPP-4 enzyme activity and DPP-4 enzyme deficiency have been associated with an increase in ACE inhibitor-induced angioedema in rats and humans, and it was hypothesized that concomitant use of DPP-4 inhibitors and ACE inhibitors could increase the risk of angioedema-related adverse events." (PMID 20412573, 2010). "Here, we present a case of angioedema affecting the lips and tongue that developed years after ACE inhibitor initiation, resulting in difficult airway management and impending cardiac arrest." (PMID 41646567, 2026).